SLC5A4 (solute carrier family 5 member 4)
Description:
Does not function as sodium/D-glucose symporter. However, may function as a D-glucose sensor by generating a D-glucose-induced depolarization which is pH-independent, Na(+)-dependent at neutral pH and probably H(+)-dependent at acidic pH.
Synonyms: SAAT1; SGLT3; DJ90G24.4
Tractability: Small molecule: a high-quality ligand is known; it belongs to a druggable protein family. Antibody: UniProt places it where antibodies can reach, with high confidence; UniProt predicts a signal peptide or a membrane-spanning region; its Gene Ontology location is reachable by antibodies, with medium confidence. PROTAC: ubiquitination databases record sites on it; a small molecule that binds it is known.
Chemical probes: CHEMBL1819489, ERTUGLIFLOZIN (high quality)
Gene: Protein-coding gene on chromosome 22 (32,218,464 to 32,255,347, reverse strand). Ensembl gene ENSG00000100191.
Subcellular location: Cell membrane
Pathways (Reactome):
Transport of small molecules: Cellular hexose transport
Gene Ontology:
Molecular function: D-glucose:sodium symporter activity; protein binding; transmembrane transporter activity; proton transmembrane transporter activity; solute:sodium symporter activity
Biological process: D-glucose import across plasma membrane; renal D-glucose absorption; proton transmembrane transport; sodium ion transmembrane transport; transmembrane transport
Cellular component: plasma membrane; membrane
Genetic constraint (gnomAD): Loss-of-function variants: 27 observed, 38.92 expected, observed/expected ratio (o/e) 0.69, 90% interval 0.51 to 0.96. The upper end of that interval is the gene's LOEUF score, 0.96, which puts it in group 4 of 6, group 1 being the genes least tolerant of losing a copy. Missense variants: 570 observed, 698.6 expected, observed/expected ratio (o/e) 0.82, 90% interval 0.76 to 0.87. Synonymous variants: 212 observed, 259.72 expected, observed/expected ratio (o/e) 0.82, 90% interval 0.73 to 0.92.
Homologues: Orthologues: chimpanzee SLC5A4 (99% identical), macaque SLC5A4 (96% identical), dog SLC5A4 (84% identical), pig SLC5A4 (82% identical), guinea pig SLC5A4 (81% identical), rat Slc5a4 (80% identical), mouse Slc5a4a (79% identical), rabbit SLC5A4 (79% identical), zebrafish slc5a8l (19% identical), Drosophila melanogaster ChT (15% identical), Drosophila melanogaster kumpel (15% identical), Drosophila melanogaster CG2187 (15% identical), and 10 more. Paralogues in human: SLC5A1 (71% identical), SLC5A2 (56% identical), SLC5A9 (51% identical), SLC5A11 (50% identical), SLC5A10 (45% identical), SLC5A3 (43% identical), SLC5A8 (20% identical), SLC5A12 (20% identical), SLC5A5 (20% identical), SLC5A6 (18% identical), SLC5A7 (15% identical).
Diseases named in the same sentence as SLC5A4 in open-access papers:
SLC5A4 is named in the same sentence as 15 diseases in open-access papers, as found by Europe PMC text mining. Sharing a sentence is not in itself a finding about the gene and the disease.
SLC5A4 shares sentences with these, for which no sentence is quoted: Hypertension (4 papers); cancer (2); Hypoglycemia (2); tumor (2); adenoma (1); atrial fibrillation (1); attention deficit-hyperactivity disorder (1); breast carcinoma (1); Cirrhosis (1); colon carcinoma (1); diabetes mellitus (1); Hyperglycemia (1); lupus nephritis (1); renovascular hypertension (1); Sepsis (1).